IL6 (interleukin 6)
Diseases named in the same sentence as IL6 in open-access papers (continued):
Sharing a sentence is not in itself a finding about the gene and the disease.
COVID-19 (continued). "Nevertheless, another study showed that in paediatric/young COVID-19 patients (n = 65, < 24 years) who generally suffer less severe disease there were increased serum levels of IFNγ and IL-17A but not of IL-6 and TNFα protein compared to adult COVID-19 patients (n = 65)." (PMID 36941580, 2023). "Similarly, found a slight and persistent alteration of D-dimer, fibrinogen, and IL-6 in a non-negligible percentage of COVID-19 patients (32.2%, 61%, and 32.2%, respectively) 3–6 months after discharge." (PMID 37671070, 2023). "Similarly, no COVID-19 plasma exposure triggered significant endothelial IL-6 production, which ranged from 23.3 ± 8.3 pg/ml to 25.6 ± 6.3 pg/ml for control plasma and 27.7 ± 10.4 pg/ml to 35.4 ± 20.8 pg/ml for TPE plasma." (PMID 37215546, 2023). "Thus, in the early stages of COVID-19, in which IL-6 plays protective roles, IL-6R inhibition would not be helpful but would be detrimental." (PMID 37818368, 2023). "The positive association between HERV-W with IL-6 expression and the negative association with IL-10 are in line with the immunopathogenic role of the ENV HERV-W protein as described in MS and recently in COVID-19." (PMID 37894766, 2023). "Moreover, most of these correlations were lost in critical COVID-19 patients except the negative correlation of IL-6 with leptin levels, and positive correlations found between IL-10 and TNFα and Resistin." (PMID 36509969, 2023). "In addition, patients with such complicated forms of COVID-19 had nearly threefold higher serum IL-6 levels than those with noncomplicated disease." (PMID 37095536, 2023). "When analyzing the COVID-19 patients age-related (cut-off median = 69 years) by dividing them into an older and younger subgroup, it has been shown that hs-CRP correlated significantly with MCP3 (r = 0.577), CCL23 (r = 0.542) and IL6 (r = 0.722, all p < 0.01) in younger COVID-19 patients." (PMID 37832397, 2023). "Therefore, we can conclude that basal hypoNa, yet not higher IL-6 levels, maintains its role in COVID-19 patients as an indicator of a more severe disease, with altered cardiologic and pulmonary profiles at follow-up." (PMID 36284058, 2023). "Both GA/18β doses modulated inflammatory response by reducing mainly IL-17A expression, which in turn kept IL-1β, IL-6, IL-8 and TNF-α interleukins unchanged, indicating significant modulation of key interleukin levels to prevent exacerbation of the immune response in COVID-19 patients." (PMID 38283346, 2023). "Therefore, the production of proinflammatory cytokines was increased in COVID-19 but did not correlate with disease severity (except for IL-6) or outcome." (PMID 37174682, 2023). "Importantly, our present study demonstrates that phagocytosis of SARS-CoV-2-infected cells is not immunologically silent but can result in the production of the proinflammatory cytokines IL-6 and TNF, both of which are known to be involved in COVID-19 pathogenesis." (PMID 37253946, 2023). "Clinical trials and reports had shown that IL-6 played an important role in the pathogenesis and severity of COVID-19, inhibiting the IL6 receptor could effectively reduce mortality or the side effects of COVID-19." (PMID 38125571, 2023). "A total of 64.3% of the patients had an acute COVID-19 condition of mild/moderate severity, and the remaining 35.7% suffered a severe condition requiring hospital admission, with expected alterations in the admission analysis (elevated levels above AST, ALT, CRP, D-dimer, and IL-6 reference values)." (PMID 37515140, 2023). "As IL-6, CRP, NLR, PLR, lymphocyte count, and eosinophil count are strongly correlated with the form of the disease, we can state that they may represent a minimum set of markers to be tested as the best predictors for the aggressive evolution of COVID-19." (PMID 36838284, 2023).
COVID-19 (continued). "Interleukin (IL) 2 and 6 (IL-2, IL-6), tumor necrosis factor-alpha (TNF-α), interferon-gamma (IFN-γ), macrophage inflammatory protein (MIP), and monocyte chemoattractant protein 1 (MCP-1) are among many other cytokines that are present in seriously ill COVID-19 patients." (PMID 36901751, 2023). "Thus, further research is needed to measure serum IL-6 levels and NLR in patients with COVID-19 using an IL-6 cut-off of >6.99 pg/mL and NLR of >4.18, which can be included in the laboratory parameters for the management of patients with COVID-19." (PMID 38099004, 2023). "The ongoing ASSAIL-MI trial has shown the potential for anti-IL-6 treatment to increase myocardial salvage in STEMI patients at the time of reperfusion, whilst previous evidence has highlighted the anti-arrhythmic potential of anti-IL-6R therapy in patients with rheumatoid arthritis and COVID-19." (PMID 37668685, 2023). "The pro-inflammatory factor IL-6 has been shown to activate the JAK/STAT signaling pathway, and more experiments are needed to prove whether other pro-inflammatory factors in COVID-19 patients have the same effect." (PMID 35774402, 2022). "In fact, especially in viral diseases, such as COVID-19, the serum levels of IL-6 and consequently of IL-8 do not seem to be high enough to induce the massive increase in the leukocyte count which is characteristic for bacterial infections or for other acute clinical situations." (PMID 36278528, 2022). "In our population, specific COVID-19 treatments like Dexamethasone or monoclonal antibodies directed against interleukin-6 (IL-6) or against SARS-CoV-2 Spike protein were not commonly used, mainly because severe infections were observed preferentially before these therapies were available." (PMID 36555978, 2022). "Additionally, we measured a significant decrease in the IL-6 concentration in the BAL, an inflammatory cytokine that correlates with disease outcomes in acute respiratory infections, including both influenza and COVID-19, in humans." (PMID 35737459, 2022). "Evidence has revealed that COVID-19 may affect the pathophysiology of diabetes through increased ACE-2 expression, increased paired basic amino acid cleaving enzyme (FURIN), impaired T-cell function, and increased interleukin-6." (PMID 35187079, 2022). "Factors that may exacerbate COVID-19 morbidity through hyperinflammatory states include increases in the complement system, increases in TLR-1 and TLR-7, and increased pro-inflammatory cytokines such as IL-6 and TNFα." (PMID 35955740, 2022). "Furthermore, the extent of inflammatory cytokine in serum, such as IL-6 and TNF-α, as well as lymphopenia, especially with respect to CD8+ T cells, positively correlates and serves as a better predictor for severity and mortality in COVID-19." (PMID 35883618, 2022). "In addition to corticosteroid use, immunomodulatory therapies inhibiting IL6 (tocilizumab/sarilumab) and Janus kinase (JAK) are recommended for managing COVID-19, with the aim of reducing the cytokine storm or inhibiting signaling required for immune activation." (PMID 36531987, 2022). "Our data provide new evidence that high levels of IL-6, sIL-6R, sgp130, binary/ternary complex ratio, and low FME are independent predictors of COVID-19 severity in survivor patients (without death), and the combination of IL-6 + sIL-6R + sgp130 exhibited the most robust classification capacity." (PMID 35634332, 2022). "In addition, the plasma concentrations of both IL-26 and IL-8 displayed a negative correlation with the mean corpuscular hemoglobin (MCH) in whole blood from the COVID-19 group, while IL-6 and TNFα failed to correlate with MCH in this way." (PMID 36466824, 2022). "If our hypotheses of inflammation driven phenoconversion holds true, this may also be relevant for IL-6-inhibitors including tocilizumab and clazakizumab that are currently being introduced into the KTR population both in COVID-19 and chronic antibody-mediated rejection." (PMID 35651879, 2022).
COVID-19 (continued). "Based on the finding of high IL-6 and TNF-alpha CSF/serum ratios and indices in the only SARS-CoV-2-IgG-AI-positive patient tested but not in any other patients, such studies should evaluate also IL-6 and TNF-alpha as supplementary markers of acute intrathecal inflammation in COVID-19." (PMID 35057809, 2022). "Therefore, IL-6 is a prognostic marker for serious COVID-19 cases in pregnant and non-pregnant cohorts." (PMID 35678023, 2022). "However, the levels of IL-6 were lower compared to those observed in sepsis (983 pg/mL), in non-COVID ARDS (460 pg/mL), and in CAR-T CRS (3110 pg/mL), suggesting that the systemic inflammation during COVID-19 is less robust." (PMID 35634332, 2022). "Overall, these results demonstrate the ability of a selected set of systemic mediators (IL-6, IFN-γ, IL-1Ra, IL-13, PDGF and IL-7) as putative laboratory markers that are applicable as complementary records in the clinical management of severe COVID-19 patients." (PMID 36451835, 2022). "Furthermore, another study reported MDSCs as the primary source of IL-6 in severe COVID-19, but administering tocilizumab (an IL-6 inhibitor) did not reduce circulating MDSC or IL-6 levels." (PMID 35401519, 2022). "In addition, the concentration of sIL-6R is high in severe COVID-19 but not correlated with IL-6 levels." (PMID 36038915, 2022). "Moreover, severe COVID-19 patients who received high-flow oxygen inhalation and mechanical ventilation during hospitalization had significantly higher baseline IL-6 levels than those without the need for oxygen therapy support." (PMID 36232655, 2022). "Similarly, alveolar capillary endothelial cells showed strong and diffuse immunoreactivity for IL-6 and IL-15, observed as red dots in the cytoplasm, in the COVID-19 group but not in the control group (p < 0.001)." (PMID 34463916, 2022). "Furthermore, a clear clustering of cytokines (IL-6, TNF-α, IFN-γ, IFN-α, SDF-1α, MIP-1α, MIP-1β, G-CSF, IL-10, CX3CL1 and IL-4) was observed in a PCA for critically ill COVID-19 patients during the first wave who presented a bacterial superinfection during their stay at the ICU." (PMID 35007290, 2022). "Moreover, IL-6 levels did not significantly differ in COVID-19 patients with a determinate or indeterminate QFT-Plus assay." (PMID 35207531, 2022). "Although implemented studies have shown that plasma IL-6 and IL-10 could be used as factors to predict the progression of COVID-19, their values could not be used separately to distinguish COVID-19 stage groups." (PMID 36438922, 2022). "Based on these observations, prevention of IL-6-mediated signaling may not be sufficient in critically ill patients with COVID-19-related CRS." (PMID 35619180, 2022). "Interestingly, IDO1 inhibitors suppress the COVID-19-induced pro-inflammatory cytokine release, including TNF-α, IL-6, IL-1α and IL-1β in isolated PBMCs derived from COVID-19-infected rhesus macaques and lower mortality among critically ill patients with COVID-19." (PMID 36589459, 2022). "Hence, the hsa_circ_0000479/hsa-miR-149-5p/IL-6, RIG-I axis might be an encouraging therapeutic target for COVID-19 patients." (PMID 36081604, 2022). "Among severe COVID-19 patients, the serum levels of IL-6 and MIP-1α are not increased proportionately compared to the moderate disease group, which may be due to the time point of the disease course at which samples were obtained from patients." (PMID 35822078, 2022). "In our study, the concentration of IL-6 could differentiate COVID-19 NAFLD from non-NAFLD patients, as well as NAFLD critical from NAFLD non-critical patients." (PMID 35743825, 2022). "Altogether, the data evidence that soluble receptors, sIL-6R and sgp130, rather than IL-6, could characterize COVID-19 severity." (PMID 35634332, 2022).
COVID-19 (continued). "High levels of IL-6, IL-10, monocyte chemoattractant protein (MCP)-1, macrophage inflammatory protein (MIP)-1α and MIP-1β are detected in bronchoalveolar lavage fluid (BALF) of COVID-19 patients, indicating inflammatory environment with high monocyte chemoattractants." (PMID 35589689, 2022). "Furthermore, it has a positive correlation with pro-inflammatory cytokines such as IL-6 and tumor necrosis factor-α (TNF-α), suggesting that Gal-9 inhibition could be a potential therapeutic approach in COVID-19 patients." (PMID 35432324, 2022). "It is possible that the immune response of COVID-19 patients is enhanced by molecular pathways different from IL6, which may play a relevant role in patients without an IL6 increase." (PMID 35783606, 2022). "In summary, the present findings provide further support for using SDC-1 alone or combined with other markers such as IL-6, TNF-α, CRP, PCT, and D-dimer as possible indicators for predicting severity and could be a valuable approach for monitoring the disease activity of COVID-19." (PMID 36556051, 2022). "IL-6 inhibition does not seem to be useful even in early stages of COVID-19, as IL-6 signalling would be protective, indeed already blocked by the virus, and mild-moderate disease would be primarily driven by viral replication and additional upstream cytokines." (PMID 35340805, 2022). "However, some tendency for a lower CRP, IL-6, PCT, and d-dimer, and a less frequent requirement for oxygen supplementation were noted in patients who received a booster at least 14 days prior to their first COVID-19 symptoms." (PMID 35455306, 2022). "Mainly, TNF, IL-6, and IL-8 were lower in COVID-19 compared to patients with septic shock/ARDS, and due to IL-6 and IL-8 was near eightfold lower, it was suggested that cytokine storm does not characterize COVID-19, and it could be one of the reasons for the immunosuppressive therapies fail." (PMID 35631442, 2022). "Therefore, increase in IL-6 and CRP might be helpful to distinguish the early stage (mild to moderate) of COVID-19 patients." (PMID 36219652, 2022). "In addition to IL-6, CRP is a significant marker of COVID-19 inflammation." (PMID 35237386, 2022). "On the other hand, the increased level of circulating IL-6 in patients with COVID-19 is not more than that in patients with autoimmune diseases, so it is unclear whether IL-6 is the contributory cytokine in COVID-19 pulmonary or not." (PMID 35619180, 2022). "Indeed, in the most severe cases of COVID-19, there is an over-expression of certain cytokines, such as IFN-gamma, TNF-alpha and IL-6, with strong pro-inflammatory action: these molecules are able to activate also the coagulative cascade with the risk of disseminated intravascular coagulation." (PMID 35807096, 2022). "Subsequently, supernatants were analyzed for IL-6 amounts, as this cytokine is primarily released from iMGL activated by RNA-based TLR7/8 agonists (data not shown) and its concentration in the cerebrospinal fluid (CSF) of a subset of COVID-19 patients is increased." (PMID 36713399, 2022). "Inflammatory cytokine (IL-6, IL-1, and IFN) blockade, stem cell therapy, immune cell reduction, transfusion of convalescent plasma, and artificial extracorporeal liver support are all potential therapies for COVID-19, and we believe that IL-6 blockade is a viable technique for COVID-induced CRS." (PMID 36506506, 2022). "However, the results of several clinical trials that investigated the benefits of IL-6 antagonists in patients with COVID-19 were not consistent." (PMID 35012610, 2022). "Limiting CRS is especially important for COVID-19 patients, who often display a cytokine storm even in the absence of such therapies, with increased levels of inflammatory cytokines and chemokines (TNF-α, IL-1, IL-6, IL-8, IL-10, IL-18, and MCP-1) that severely damage pulmonary tissue." (PMID 35546150, 2022).
COVID-19 (continued). "Evaluating the serum levels of IP-10, MCP-1, MIP-1α, and IL-6 and genotyping of rs12252 SNP of IFITM3 gene among different categories of COVID-19 patients might aid in understanding the pathogenesis of COVID-19 and contribute to developing disease-specific biomarkers and therapeutic strategies." (PMID 35822078, 2022). "In early stages of COVID-19, in which IL-6 may play protective roles, IL-6R blockade would not be useful either." (PMID 35340805, 2022). "Although, various drugs that control the cytokine storm, such as corticosteroids, anti-IL-6 antibodies, and Janus kinase inhibitors, are thought to be effective against severe COVID-19, some patients with severe disease do not recover with these drugs alone or in combination." (PMID 35361913, 2022). "Importantly, strong increase in PGE2 and in IL-6/IL-8/IL-1β cytokines was observed in monocytes activated with DD in the presence of IC of PVCoV-2 coated with plasma from hospitalized COVID-19 patients but not from healthy donors." (PMID 35385545, 2022). "In patients with severe COVID-19, a hyperinflammatory response to SARS-CoV-2 occurs due to a dysregulated innate host immune response, with increased levels of proinflammatory cytokines (IL-1, IL-6, TNF-α) and other acute phase reactants (CRP, D-dimer or ferritin)." (PMID 36012968, 2022). "The DPP4 inhibitor also improves bronchoalveolar lavage IL-6 and TNF-α levels in LPS-induced mice and attenuates lung injury, meaning direct stimulation of anti-inflammatory activity in the lungs may help ameliorate lung damage from COVID-19." (PMID 36341356, 2022). "Interestingly, the IL-6/STAT3 axis could contribute to an exacerbated immune response and COVID-19 complications such as thrombosis and lung fibrosis." (PMID 35327634, 2022). "Moreover, the levels of pro-inflammatory cytokines such as interleukin-6 (IL-6), IL-8 and TNF-α tended to be increased in severe COVID-19 patients, which could also be indicators of the disease progression." (PMID 36110850, 2022). "Across all the soluble proinflammatory markers we examined, ICAM, IL-1β, IL-4, IL-6, TNFα, and Syndecan showed a statistically significant positive correlation between cytokine or epithelial marker and antibody quantity regardless of COVID-19 disease severity." (PMID 36865568, 2022). "During lung inflammation followed by ARDS, the activation of the IL6-mediated positive feedback loop of NF-κB signaling in non-immune cells such as fibroblasts known as IL6 amplifier plays a critical role in inducing cytokine storm as observed in severe COVID-19 patients." (PMID 35941890, 2022). "Additionally, IL-6 was not elevated, and systemic COVID-19 illness was not severe, both of which would have been expected in cytokine-mediated HE." (PMID 35453972, 2022). "In our study, the cytokines IL-6, IL-10, and TNF-α were significantly upregulated in severe COVID-19 patients, especially in male patients, indicating that IL-6 antagonists and TNF-α inhibitors are more appropriate used in male patients to reduce both severity and mortality rate of COVID-19." (PMID 35237162, 2022). "In the current study, any genotype associated with IL6 rs1800796, IL-10 rs1800896, TNF -α rs1800629, and IFITM3 rs12252 SNPs was significantly different between COVID-19 survivors with and without post-COVID pain, and, therefore, also with different pain phenotype features." (PMID 36233516, 2022). "Indeed, cytokine blockade was not effective in COVID-19-unrelated ARDS (showing higher IL-6 levels but much lower CRP values as compared to severe COVID-19), while it is effective in CAR T-cell induced CRS (showing high concentrations of both IL-6 and CRP)." (PMID 35340805, 2022). "When it comes to P2Y12 Receptor Antagonists, there is not much evidence of their COVID-19 use, however, its administration in cases of pneumonia can lead to a decrease in circulating platelet and leukocyte count, lower IL-6 levels and improved lung function and oxygen requirements." (PMID 36295093, 2022).